CD28 (CD28 molecule)
Diseases named in the same sentence as CD28 in open-access papers (continued):
Sharing a sentence is not in itself a finding about the gene and the disease.
Osteopenia (2 papers, 2017 to 2021). Osteopenia is a term to define bone density that is not normal but also not as low as osteoporosis. "The number of CD3+CD28+ activated T-lymphocytes and CD19-HLADR+CD123+ plasmacytoid DCs were meaningly lower in women with osteopenia (2." (PMID 28696349, 2017).
polymyositis (2 papers, 2011 to 2024). A rare idiopathic inflammatory myopathy characterized by symmetric proximal muscle weakness and elevated muscle enzymes. "Specifically, polymyositis demonstrated the capacity to decrease the levels of 2 immune cell types (OR < 1, P < .05): B cell panel: CD28 on secreting CD4 regulatory T cell and myeloid cell panel: CD45 on CD33‐ HLA-DR‐." (PMID 39470507, 2024). "Several immune cell phenotypes exhibited the ability to increase the risk of polymyositis, such as PB/PC %B cells, CD86+ myeloid DCs, and CD28 on Treg cells." (PMID 39470507, 2024).
prediabetes (2 papers, 2019 to 2026). "We also found that activated CD8+CD28− T cells using anti-CD3 antibodies showed a higher ECAR in the patients with prediabetes than in normal controls, suggesting that metabolically higher glycolytic potential of CD8+CD28− T cells is visible in the patients with abnormal glucose homeostasis." (PMID 30867412, 2019). "To compare the immunosenescence of T cells in PBMCs from normal controls and patients with prediabetes, we evaluated the frequency of CD57+ and/or CD28− T cells among the CD4+ and CD8+ T cells in the PBMCs from the study population." (PMID 30867412, 2019). "CD4+CD28− T cells contained similar concentrations of ROS, regardless of serum glucose status, whereas CD8+CD28− T cells from the patients with prediabetes had a higher capacity to produce ROS than those from normal subjects." (PMID 30867412, 2019). "Therefore, we measured the oxygen consumption rate (OCR) and extracellular acidification rate (ECAR) in CD8+CD28− T cells from normal subjects and the patients with prediabetes, and found no marked difference in the OCR of CD8+CD28− T cells between these groups." (PMID 30867412, 2019).
primary sclerosing cholangitis (2 papers, 2017 to 2022). "The CD28 locus is associated with susceptibility to a variety of autoimmune and immune-mediated inflammatory diseases including primary sclerosing cholangitis (PSC)." (PMID 28794437, 2017). "Moreover, vitamin D plays an important role in regulating T-cell-mediated immunity as it reversed inflammatory CD28- T cells accumulate in livers of patients with primary sclerosing cholangitis and localize around bile ducts." (PMID 36605198, 2022).
psychosis (2 papers, 2016 to 2021). "Previous studies have reported that the number of CD4+CD27+CD28+ cells in elderly patients with psychosis is lower than that in young patients." (PMID 34955935, 2021).
pulmonary sarcoidosis (2 papers, 2020 to 2025). Sarcoidosis affecting the lung parenchyma. "In the overlapping canonical pathways analysis of BALF proteins in progressive and non-progressive cases, CD28, CDC-42 and IL-8 signaling, and Th1 pathways had high-connectivity suggesting a central role of these pathways in the progression of pulmonary sarcoidosis." (PMID 32764642, 2020).
Salmonella Infections (2 papers, 2008 to 2024). Infections with bacteria of the genus SALMONELLA. "However, the anti-CD3/CD28 stimulated IFN-γ and IL-10 response was significantly attenuated following Salmonella infection in the B. infantis-fed animals." (PMID 18670628, 2008).
sarcopenia (2 papers, 2025). Progressive decline in muscle mass due to aging which results in decreased functional capacity of muscles. "TNF-α is implicated not only in the pathogenesis of sarcopenia but also in the downregulation of CD28 expression on T cells, leading to the accumulation of CD28—T lymphocytes, a hallmark of immune aging that contributes to a vicious cycle of sarcopenia." (PMID 40852355, 2025). "Specific subsets of lymphocytes, such as CD4 + CD28 null T cells, have been found to be negatively correlated with muscle mass, suggesting their involvement in muscle degradation in sarcopenia." (PMID 40904783, 2025).
sialadenitis (2 papers, 2020 to 2023). Sialadenitis is an infection of the salivary glands. "Similar to NOD mice, NOD.CD28-/- mice also develop sialitis." (PMID 37593744, 2023).
Sjögren's syndrome (2 papers, 2012 to 2022). "In summary, our data suggest that inhibition of the costimulatory pathway CD28 by expression of CTLA4IgG locally in the salivary gland can be a useful approach for reducing the inflammation and improving the secretory activity associated with Sjögren's syndrome." (PMID 22369699, 2012). "Ocular surface disease was assessed by quantifying corneal epithelial damage with lissamine green stain in the NOD.H-2h4,IFNγ−/−,CD28−/− (NOD.H-2h4 DKO) mouse model of Sjögren's syndrome (SS)." (PMID 35727180, 2022).
smooth muscle tumor (2 papers, 2020 to 2025). A benign or malignant myomatous neoplasm arising from smooth muscle. "CARMIL2 deficiency causes defective CD28-mediated T cell co-stimulation, altered cytoskeletal dynamics, susceptibility to various infections and an Epstein–Barr virus-induced smooth muscle tumor (EBV-SMT)." (PMID 39873967, 2025).
systemic inflammatory response syndrome (2 papers, 2018 to 2019). SIRS is a serious condition related to systemic inflammation, organ dysfunction, and organ failure. "Previous attempts to directly influence T cells in humans resulted in a life-threatening systemic inflammatory response syndrome, leading to multiorgan failure after administration of an anti-CD28 monoclonal antibody." (PMID 31383034, 2019).
tuberculosis (2 papers, 2015 to 2023). A chronic, recurrent infection caused by the bacterium Mycobacterium tuberculosis. "Therefore, the second signal of CD28 decreased expression which causing weakened T lymphocyte activation in patients with active tuberculosis, it may be one of the mechanisms of immune escape in this bacterium." (PMID 37103584, 2023). "However, mechanisms of action of M. tuberculosis antigens (specifically Ag85A and ESAT-6) on TCR/CD28 mediated signalling in TB patients have not been addressed till date hence needs to be investigated." (PMID 26552486, 2015).
viral hepatitis (2 papers, 2013 to 2016). An acute or chronic inflammation of the liver parenchyma caused by viruses. "In viral hepatitis (HCV and HBV), IH-CD8+ T-cells frequently have an activated phenotype (i.e. decreased CD28 and increased IFN-γ expression), similar to the TCM/TEM type phenotype of the IH-CD8+ T-cells observed here." (PMID 27315061, 2016).
Zinc deficiency (2 papers, 2024). A deficiency of the essential metal Zinc; an essential cofactor for many enzymes. "A review found that zinc deficiency can affect adaptive T-cell immunity, leading to the down-regulation of CD28, and the complete loss of classical auxiliary function (Sub)." (PMID 38693478, 2024). "For example, in zinc deficiency, the IFN-γ production is decreased; therefore, we investigated whether the additional increase in zinc after CD3 + CD28 stimulation, compared to CD3 stimulation alone, would also enhance IFN-γ expression." (PMID 38673887, 2024).
acute hepatitis C (1 paper, 2009). "The role of CD28 in the functional response to PD-1/CTLA-4 blockade was further examined in an HLA-A2+ patient with acute hepatitis C using an HLA-A2/peptide tetramer." (PMID 19247441, 2009).
acute respiratory failure (1 paper, 2021). Life-threatening respiratory failure that develops rapidly. "Notably, a clinical trial conducted at NCI to test third-generation HER2 CAR-T cells (CD28/4-1BB/CD3ζ) in patients with metastatic cancers (NCT00924287); however, the trial was terminated after a patient with CRC died of severe acute respiratory failure as a result of the treatment." (PMID 34839348, 2021).
acute tonsillitis (1 paper, 2020). An acute inflammation of the tonsils caused by viruses or bacteria. "The aim of this study was to examine T cell function in tonsils of patients with recurrent acute tonsillitis (RAT) or peritonsillar abscess (PTA) by analyzing the cytokine production following T cell receptor (TCR) and co-receptor stimulation with a combination of anti-CD3 and anti-CD28 antibodies." (PMID 32747802, 2020).
adult respiratory distress syndrome (1 paper, 2020). "In one published incident, fatal adult respiratory distress syndrome occurred rapidly following infusion of > 1010 T-cells, targeted against ErbB2 using a trastuzumab scFv coupled to a fused CD28/4-1BB/CD3ζ endoplasmic domain." (PMID 31910217, 2020).
age (1 paper, 2017). A temporal measurement of the time period elapsed since an identifiable point in the life cycle of an organism. "It has been previously reported that the accumulation of CD28− T cells is associated with age-related decline of immune function." (PMID 28754961, 2017).
amyloid (1 paper, 2025). "Lowering PU.1 expression in microglia reduces the severity of amyloid disease pathology in mice and is linked to the expression of immunoregulatory lymphoid receptor proteins, particularly CD28, a surface receptor that is critical for T cell activation." (PMID 41193812, 2025). "Microglia-specific deficiency in CD28, which is expressed by a small subset of plaque-associated PU.1low microglia, promotes a broad inflammatory microglial state that is associated with increased amyloid plaque load." (PMID 41193812, 2025).
antibody deficiency (1 paper, 2025). "Although our patient presents CD4+ T cell lymphopenia and antibody deficiency, we assessed normal CD4+ and CD8+ cell proliferation with CD3/CD28 and in B cells with both T cell dependent stimuli (CD40L and IL-21) and the combination of T cell dependent and independent stimuli." (PMID 40170851, 2025).
aortic aneurysm (1 paper, 2022). A ruptured aneurysm located in the wall of the proximal portion of the descending aorta proceeding from the arch of the aorta. "FOXP3+ Treg cells were abundant in aortic aneurysms, especially in AAA groups and displayed high expression of exhausted genes CTLA4, TIGIT, TNFRSF14, ICOS, and CD28." (PMID 36703732, 2022).
appendicitis (1 paper, 2023). Acute inflammation of the vermiform appendix. "T cells in complex appendicitis displayed an increased differentiated phenotype compared to simple appendicitis, including a loss of both CD27 and CD28 by CD4+ T cells and to a lesser extent by CD8+ T cells." (PMID 38239362, 2023). "This augmented pro-inflammatory activity of CD4+ T cells in complex appendicitis is in line with the reduced expression of CD27 and CD28 indicating an increased effector phenotype of CD4+ T cells in the appendix of children with complex compared to simple appendicitis." (PMID 38239362, 2023).
asbestosis (1 paper, 2021). A lung disorder caused by inhalation of asbestos fibers. "Activated T cells were detected in patients with asbestosis and silicosis, and these cells exhibited lower CD28 expression and higher HLA-DR expression." (PMID 34022844, 2021). "CD28 expression was significantly decreased on CD8+ T cells in PB from patients with asbestosis, while CD69 and HLA-DR expression was significantly increased on CD8+ T cells in PB from these patients." (PMID 34022844, 2021). "The percentages of circulating CD28+CD8+ T cells were significantly lower in patients with asbestosis and silicosis than in the healthy controls (P < 0.05), and the percentages of circulating HLA-DR+CD8+ T cells were significantly higher in both groups than in the healthy controls (P < 0.05)." (PMID 34022844, 2021). "Interestingly, the percentage of PD-1+ CD8+ T cells was positively correlated with the percentage of CD28+ CD8+ T cells in PB from patients with asbestosis and silicosis." (PMID 34022844, 2021). "In addition, the proportions of CD8+ PD-1+ T cells were positively correlated with the proportions of CD8+ CD28+ T cells in the PB of patients with asbestosis." (PMID 34022844, 2021).
atopic dermatitis (1 paper, 2013). "It was presumed that these antibodies stimulate T cells and may play an important role in chronic allergic inflammation as sera from patients with atopic dermatitis containing CD28 abs were able to stimulate T cell proliferation in vitro." (PMID 23483974, 2013). "It was assumed that these antibodies stimulate T cells and may play an important role in chronic allergic inflammation, as sera from patients with atopic dermatitis containing CD28 abs were able to stimulate T cell proliferation in vitro." (PMID 23483974, 2013).
Atrophy (1 paper, 2021). Any weakening or degeneration, especially through lack of use. "S. japonicum can also induce thymic atrophy with the accumulation of both CD8+CD28- T cells and CD4+CD28- T cells." (PMID 34113341, 2021).
autism (1 paper, 2022). Persistent deficits in social interaction and communication and interaction as well as a markedly restricted repertoire of activity and interest as well as repetitive patterns of behavior. "Studies on PBMCs and CD4+ T cells consistently showed differential responses from these cells in autism when stimulated with PMA/ionomycin and anti-CD3/CD28, respectively, as compared with the control group." (PMID 36268027, 2022). "Therefore, the use of PMA/Ionomycin and anti-CD3/CD28 to stimulate PBMCs and CD4+ T cells, respectively, may represent a good model for studying cytokine production in autism." (PMID 36268027, 2022).
autoimmune encephalitis (1 paper, 2022). Inflammation of the brain secondary to an immune response triggered by the body itself. "SIR1 knockout mice show increased susceptibility to autoimmune encephalitis, and CD28 affects T-cell proliferation in mice." (PMID 35350434, 2022).
autoimmune peripheral neuropathy (1 paper, 2017). "In case of autoimmune neuromyopathy, the need for pre-activation of effector T-cells in vitro using anti-CD3 and anti-CD28-coated microplates prior to transfer has been reported when transferring autoimmune peripheral neuropathy by T lymphocytes from B7.2−/− NOD donors." (PMID 28424681, 2017).
autoimmune uveitis (1 paper, 2017). An autoimmune form of uveitis (disease). "Here we show that specific CD28 blockade, is a promising strategy for treating autoimmune uveitis, and that PV1 is a useful tool for dissecting the cellular events involved in this phenomenon." (PMID 28248972, 2017). "In this study we show that the selective blockade of CD28 using a monovalent Fab fragment is effective in the treatment of experimental autoimmune uveitis acting directly on effector T cells, specifically dampening IFN-γ production with no induction of anergy or enhancement of Treg cell activity." (PMID 28248972, 2017).
biliary tract cancer (1 paper, 2024). "The detection result for CD45RA- CD28- CD8br%CD8br was an odds ratio of 1 (95% CI=1.00–1.00, P=0.009), with similar outcomes observed using MR-Egger and Weighted Median,indicating that this immunophenotype has no impact on the risk of biliary tract cancer." (PMID 39050844, 2024).
Blau syndrome (1 paper, 2020). Blau syndrome (BS) is a rare systemic inflammatory disease characterized by early onset granulomatous arthritis, uveitis and skin rash. "As with Nod2−/− memory T cells in mice, which showed increased expression of Ccr7 in response to TCR-ligation, CD3/CD28 stimulation also increased expression of CCR7 on CD4+ T cells similarly in both the patients with Blau syndrome compared to healthy controls." (PMID 33106495, 2020).
bone metastasis (1 paper, 2024). Transfer of a neoplasm from its primary site to bones. "Furthermore, there was a negative correlation between changes in pTCD8+CD28- and bone metastasis (coefficient = −0.218, P = 0.006)." (PMID 38519706, 2024).
brain inflammation (1 paper, 2019). "We, therefore, predict that CD28 deficiency may ameliorate thoracic blast exposure-induced brain inflammation." (PMID 31885821, 2019).
brain injury (1 paper, 2019). Acute and chronic (see also brain INJURIES, CHRONIC) injuries to the brain, including the cerebral hemispheres, CEREBELLUM, and brain STEM. "Our results indicate that CD28 deficiency has a protective effect on thoracic blast exposure-induced brain injury that might be associated with the PI3K/Nrf2/Keap1 signaling pathway." (PMID 31885821, 2019). "We also examined CD28 knockout (CD28−/−) mice to study whether CD28 could be a therapeutic target in thoracic blast exposure-induced brain injury." (PMID 31885821, 2019).
bronchiolitis obliterans syndrome (1 paper, 2015). A lung disorder that is mainly associated with chronic allograft dysfunction after lung transplantation and that is characterized by inflammation and fibrosis of bronchiolar walls that reduce the diameter of the bronchioles and result in progressive and irreversible airflow obstruction. "An upregulation of cytotoxic T-lymphocyte-associated protein 4 (CTLA-4 = CD152) was detected on CD4+CD28− T cells from healthy subjects and patients with bronchiolitis obliterans syndrome." (PMID 25834833, 2015). "Contrary to these findings a newer study showed an increase of CD40L in CD4+CD28− T cells in bronchiolitis obliterans syndrome." (PMID 25834833, 2015). "The molecules 4-1BB and CTLA-4 are responsible for the production of cytotoxic T cells before or during graft rejection and OX40 and CD40L are important for proliferation and cytokine production of CD4+CD28− T cells in bronchiolitis obliterans syndrome." (PMID 25834833, 2015). "Future studies will address the question if expression of CD40L is unique for CD4+CD28− T cells in bronchiolitis obliterans syndrome or not." (PMID 25834833, 2015).
brucellosis (1 paper, 2008). Brucellosis is a bacterial infection that spreads from animals to people via unpasteurized dairy products or by exposure to contaminated animal products or infected animals. "When westudied CD80/CD28 costimulation in human brucellosis, it was indicatedthat heat-killed B.abortus (HKBA) significantly downregulated the PHA-induced increase ofCD80+ monocytes." (PMID 19190764, 2008). "Itcould be assumed that in chronic relapsing brucellosis patients prior exposuresto Brucella LPS, as a result of relapses during the chronic stage, leads to “crosstolerance” (low percentage of CD4+/CD28+ T-cells) to further in vitro E.coli LPS challenge." (PMID 19190764, 2008). "Previously,we stimulated PHA-cultured PBMCs from brucellosis patients with HKBA in orderto investigate any possible effect of brucellar antigen/s (mainly LPS) on theexpression of CD25 and CD80/CD28 costimulation molecules." (PMID 19190764, 2008).
Candidemia (1 paper, 2016). A form of invasive candidiasis where species of CANDIDA are present in the blood. "Compared to control patients, CD8 T cells from patients with Candidemia had evidence of cellular activation as indicated by increased CD69 expression while CD4 T cells had decreased expression of the major positive co-stimulatory molecule CD28." (PMID 26786705, 2016). "In contrast to the increase in inhibitory receptor/ligands noted in CD8 T cells, there was a significant decrease in the percentage of CD4 T cells expressing CD28, a major positive co-stimulatory molecule, in patients with Candidemia compared to controls, 79.8 % versus 92.6 %, respectively; p <0.05." (PMID 26786705, 2016).
cervical dysplasia (1 paper, 2020). "We still observed significant correlation of two immune co-stimulatory molecules, CD40 and CD28, with the level of genital inflammation across patients with HPV infection, cervical dysplasia, and healthy controls." (PMID 32802959, 2020).
Chagas cardiomyopathy (1 paper, 2022). A disease of the cardiac muscle developed subsequent to the initial protozoan infection by trypanosoma cruzi. "Thus, we suggested that this CTLA-4-mediated suppression mechanism could be used by Treg cells only in IND, but not by CARD patients, since Chagas cardiomyopathy patients demonstrated a higher frequency of Treg CD28+ lymphocytes and not CTLA-4, as shown by IND patients in our previous studies." (PMID 35665256, 2022).